TNF (tumor necrosis factor)
Diseases named in the same sentence as TNF in open-access papers (continued):
Sharing a sentence is not in itself a finding about the gene and the disease.
tumor (continued). "In another setup, monocytic-cell-derived TNFα upregulated CCL2 secretion from tumor cells, which then promoted TNFα secretion from monocytic cells, thereby forming a vicious circle of cross-regulation that may contribute to tumor progression and malignancy." (PMID 31921102, 2019). "Based on the literature and our previous findings, we hypothesized that suppression of ANO1 results in enhancement of caspase upstream pathways such as TNF-α signaling, subsequently leading to inhibition of tumor proliferation and metastasis." (PMID 29899325, 2018). "It has been hypothesized that TNF-α induces the production of soluble factors that promote tumor angiogenesis." (PMID 30061485, 2018). "TLR stimulation can result in NF-κB-mediated survival and the expression of pro-inflammatory mediators (including IL-1β and TNFα) which may aid in tumour cell adherence, angiogenesis and metastasis." (PMID 29415982, 2018). "TNF-α can stimulate other cytokines such as IL-17 to directly promote tumor growth." (PMID 29706964, 2018). "TNF-α initiates signaling pathways that activate proinflammatory gene expression via the transcription factor; nuclear factor-kappa B (NF-κB) is also produced by tumors and acts as an endogenous tumor promoter." (PMID 29951534, 2018). "All the tumor model studies measured markers of the immune system, such as TNF-α and interleukins." (PMID 30581489, 2018). "This correlation between TNF-α and tumor grade is also seen in severe ovarian tumors." (PMID 29467927, 2018). "In vivo, the intravenous injection of DAB-Lf dendriplex encoding TNFα led to a tumor suppression for 70% of PC-3 and 50% of DU145 tumors, while treatment with DAB-Lf dendriplex encoding TRAIL led to tumor suppression of 40% of PC-3 tumors and 20% of DU145 tumors." (PMID 29493296, 2018). "Changes in Ca2+ signalling may impair cytokine production, including Interferon (IFN)-γ and Tumor Necrosis Factor (TNF), therefore interfering with systemic inflammation and anti-tumour responses." (PMID 30134818, 2018). "Additionally, both TGF-β and TNF-α participate in the creation of inflammatory environments that enhance tumorigenesis and immunosuppressive activity blocking the host’s anti-tumour response." (PMID 30558665, 2018). "It is likely that additional spatially restricted factors, including graded morphogens, such as Wg, Decapentaplegic (Dpp), or Hedgehog (Hh), may influence “tumour hot-spots” and, therefore, the potential impact of TNF-α in this context." (PMID 29725601, 2018). "Furthermore, γδ T cells secrete pro-inflammatory cytokines, such as TNFα and IFNγ, upon activation by tumor cells." (PMID 30038626, 2018). "TNF-α is one of the most significant mediators involved in tumor cell death by the induction of multiple intracellular pathways, including the generation of reactive oxygen intermediates in the mitochondria preceding plasma membrane permeabilization and the induction of iNOS expression." (PMID 29448931, 2018). "N1 TANs were cytotoxic to tumour cells via an oxygen radical-dependent mechanism and had increased tumour necrosis factor alpha (TNF-α) and intercellular adhesion molecule 1 (ICAM-1) expression, whereas N2 TAN expressed high levels of arginase which is known to suppress T cell immunity." (PMID 30137312, 2018). "Additionally, reduction of the number of lymphocytes results in decreased release of cytokines, such as interferon and tumor necrosis factor-α by tumor macrophages." (PMID 29618336, 2018). "TNFα was first identified as a tumor cytotoxic agent that promotes cancer cell apoptosis." (PMID 29416846, 2018). "Further on, we could demonstrate that tumor bearing lungs from STAT1 KO mice are significantly less infiltrated by CD8+ TNFα+ T cells compared to tumor bearing Bl6/C57j mice." (PMID 30647851, 2018).
tumor (continued). "On the other hand, other reports indicate that the activation of NF-κB is also required for tumor development in many cancer models, due to the release of proinflammatory cytokines such as TNF-α and IL-6, which can trigger prosurvival signals for tumor cells supporting their growth and progression." (PMID 28660349, 2018). "Thus TNF-alpha, appeared to not only be a potent mediator of tumor regression, but also an effector of cachexia, and a contributor to one of the main mechanisms leading to septic shock." (PMID 30170620, 2018). "Furthermore, this pre-metastatic niche provides a platform of chemokines (IL1, IL6 and TNFα), growth factors and adhesion molecules, enabling circulating tumour cells to engraft the secondary site." (PMID 30577495, 2018). "However, it was found in another study that stimulation of the monocytic cell line THP1 with tumor-exosomes induced TNF-α, IL-1β, and IL-6 through TLR2 and TLR4 signaling." (PMID 29867942, 2018). "In contrast to TNFR1, TNFR2 diverts the tumor-inhibiting TNF into a tumor-advocating factor." (PMID 29892300, 2018). "Importantly, chemotherapy induced endothelial cells to produce tumor necrosis factor-α (TNF-α), leading to chemoresistance by “hyperactivating” the system of myeloid cell-stimulated tumor growth and metastasis." (PMID 29601539, 2018). "Vertebrate macrophages can promote tumor induction of MMPs and invasion by secreting TNFα." (PMID 29321168, 2018). "Moreover, soluble factors, such as TGFβ, tumor necrosis factor α (TNFα), and IL-6, secreted by the fibroblasts can mediate contact-independent tumor suppression in a paracrine manner." (PMID 29883428, 2018). "Tumor-targeted delivery of TNFα has been attempted by gene therapy approaches." (PMID 29468364, 2018). "While IFN-γ production may directly inhibit tumor growth in synergy with TNF-α, it remains to be investigated whether CD103+CD4+ TILs are equally equipped to kill cancer cells as their CD103+CD8+ counterparts." (PMID 30505306, 2018). "Indeed, the upregulation of adhesion molecules and chemokines on tumor vessels induced by the selective delivery of TNF (NGR-TNF) to these vessels has shown to increase the recruitment of endogenous or adoptively transferred T cells." (PMID 30405637, 2018). "Moreover, depletion of Treg cells was associated with functional maturation of CD8 and CD4 T cells, as demonstrated by increased interferon γ-producing cells and tumor necrosis factor α-producing T cells within tumor microenvironment but not in the spleen." (PMID 29472691, 2018). "However, the transfection of miR‐130b inhibitors into the tumour cell prior to TNF‐α treatment resulted in the increment in apoptosis rate as compared with the transfection of the scrambled controls of inhibitors." (PMID 29632814, 2018). "These authors stated that TNF-α targeting might be useful as a novel approach to anti-tumor therapies." (PMID 30518097, 2018). "Treatment of PC-3 tumors with the three dendriplex formulations (DAB-Lf dendriplexes encoding TNFα, TRAIL, or IL12) was characterized by a high variability of response to treatment within the same group of mice and an overall reduced tumor growth compared to naked DNA treatment." (PMID 29493296, 2018). "Indeed, eosinophils were induced to produce TNF-α, IL-6 and likely others tumor-promoting cytokines upon stimulation with IL-17." (PMID 30510245, 2018). "In contrast, low-dose paracrine TNF-α production in tumor areas may support chronic inflammation and cancer progression." (PMID 29896191, 2018). "The TNF-α/NF-κB pathway plays an important role in tumor cell invasion and metastasis." (PMID 29531823, 2018). "TNFα has shown an antitumor effect on tumor cells or tumors in combination with other treatments." (PMID 29721152, 2018). "Similarly, TNF-α-stimulated upregulation of ICAM-1 in peritoneal mesothelial cells has been described in an animal tumour mode." (PMID 29772648, 2018).
tumor (continued). "Since both TNF-α and TRAIL are potential signaling molecules involved in bystander effects, the blocking of the PI3K pathway may predispose the tumor cells to be more sensitive to bystander effects." (PMID 29719632, 2018). "Subsequent advancements largely evolved from Lloyd J. Old‘s contributions and seminal discovery of the tuberculosis Bacille Calmette-Guerin (BCG) vaccine and tumor necrosis factor, and Thierry Boon’s observation of immune recognition by T-cells of mutagen-altered tumor antigens." (PMID 30103457, 2018). "TNFα may be produced in response to inflammation and infection by macrophages, lymphocytes, fibroblasts, and keratinocytes, but also tumor cells may be a relevant source." (PMID 30154786, 2018). "M1 TAMs exert anti-tumor effects through the release of pro-inflammatory cytokines (IL-1, IL-6, IL-23, TNF-α), whereas M2 TAMs may drive local immune suppression by producing IL-10 and TGF-β." (PMID 29844297, 2018). "In our study we focused on TNF, a major inflammatory cytokine originally documented as capable to provoke, in experimental cancers, haemorrhagic necrosis, but subsequently found to paradoxical act as a tumour-promoter." (PMID 30065253, 2018). "Loss of STAT1 in the host was found associated with increased tumour load, inhibition of the anti-tumour immune responses and by the upregulation of the immune suppressive markers PD-1 in TIL and PD-L1 in TAM as well as dysfunctional TNFα immune responses." (PMID 30647851, 2018). "After disruptions of the HUVEC monolayer by TNF-α or co-culture with tumor HCT-116 in the receptor well, up to 28% of the nanocarriers could cross it." (PMID 30311803, 2018). "Similarly, TNF-α mediates anti-tumor immunity through simultaneous recruitment and activation of macrophages and DCs." (PMID 30631327, 2018). "TNF-α has been widely recognized as an important regulator of the tumor microenvironment." (PMID 29531823, 2018). "TNFα blocking agents may not only find a place as anti-tumor agents, but may have a role in controlling the severe cancer pain associated with metastatic bone lesions." (PMID 29946544, 2018). "In malignant diseases, PD-1 ligands become upregulated on leukocytes in the tumor microenvironment by various pro-inflammatory cytokines, e.g. interferon γ, interleukin 10, and tumor necrosis factor α, produced by tumor cells and other leukocytes such as T cells." (PMID 30261066, 2018). "For example, TNF-α enhances leukocyte recruitment to inflammatory sites and promotes infiltration of cytotoxic T cells into the tumor vicinity and TLR2-mediated production of IL-12 and TNF-α by macrophages results in NK cell activation and induction of the adaptive immune response." (PMID 29588627, 2018). "Like IL-12, TNFα is a proinflammatory and immunostimulatory cytokine, but in contrast to IL-12, its antitumor activity is based primarily on its direct cytotoxicity to tumor cells and vascular disruption effects." (PMID 29468364, 2018). "Indeed, when we combined the TNFα with IL-12 treatment, the therapeutic effectiveness increased significantly, as demonstrated by a pronounced tumor growth delay of 27 days, compared to only 6 days after TNFα monotherapy and 16 days after IL-12 monotherapy." (PMID 29468364, 2018). "In contrast, the pro-inflammatory cytokines like interleukin-6 (IL-6), IL-1, and tumor necrosis factor alpha (TNF-α) secreted by tumor cells may inhibit TG synthesis." (PMID 30400953, 2018). "MDSCs can produce IL-10, and TNF-α to influence their cross-talk with macrophage and tumor cells." (PMID 30166607, 2018). "TNF-α overexpression induces DNA damage leading to tumor growth, angiogenesis, and invasion." (PMID 29706964, 2018). "Interestingly, TNF-α signaling causes NF-κB to have anti-apoptotic effects, protecting the proliferating tumor cells; inhibition of NF-κB sensitizes tumor cells to TNF-α-induced apoptosis." (PMID 29907126, 2018). "Tumor necrosis factor (TNF) is an important regulator of the tumor microenvironment." (PMID 29762501, 2018).
tumor (continued). "Moreover, CSL when administered either alone or in combination with bortezomib inhibited MM tumor growth and decreased serum IL-6 and TNF-α levels." (PMID 29773987, 2018). "Similar to our results in naïve mice, we found a strong downregulation of Nos2 expression in Stat1 deficient M1 macrophages derived from tumor bearing mice as well as decreased secretion of soluble TNFα in the supernatant derived from M1 macrophages differentiated from tumor bearing STAT1 KO mice." (PMID 30647851, 2018). "Indeed, IL-33 expression in several cancers affects the number of CD8+ T cells and NK cells in tumor tissues and the production of IFN-γ/TNF-α, thereby favoring tumor eradication through tumor cell cytolysis." (PMID 30416507, 2018). "For instance, the pro-inflammatory cytokines IL-1 and TNF-α promote tumor growth." (PMID 29983866, 2018). "In some cases, the expression of ABC transporters and the consequent acquisition of a chemoresistant phenotype stems from OXPHOS-driven inflammatory reactions culminating in the secretion of interleukin 6 (IL6) and tumor necrosis factor (TNF) into the tumor microenvironment." (PMID 29219147, 2018). "CAR33VH and My96CAR elaborated high levels of IFNγ, TNFα, and IL-2 in response to CD33high tumor lines MOLM-14 and HL-60, whereas CAR T-secreted cytokines were not significantly induced when challenged with CD33moderate line KG-1a, or CAR T cells incubated alone, demonstrating antigen specificity." (PMID 30524966, 2018). "TNF- α enhances the immune function and induces apoptosis of tumor cells." (PMID 30693034, 2018). "Current findings suggest that tumor growth might be inhibited by targeting the immunosuppressive milieu through local delivery of R848, IFNγ, or TNFα." (PMID 29632539, 2018). "Notably, high levels of TNFα have been correlated with tumor stage, extent of para-neoplastic complications, and worse survival." (PMID 29946544, 2018). "We found that higher Lnc-IL7R level corresponded to lower TNF-α level in tumor tissues." (PMID 29720427, 2018). "However, TNF-α also can contribute to chronic inflammation and promote tumor formation, growth, and metastasis." (PMID 29361917, 2018). "The history of TNF-alpha is very closely related to the history of tumor immunotherapy." (PMID 30170620, 2018). "TNF-α is produced by macrophages and activates inflammatory processes during tumor promotion." (PMID 29467927, 2018). "Furthermore, co-treatment of resveratrol with 5-FU (1 nM) alone or as combinational treatment with 5-FU (1 nM) and TNF-β or TNF-α significantly increased nuclear fragmentation and apoptosis in all tumor cells." (PMID 30002278, 2018). "Tumor resistance to the cytotoxic effects of TNF-alpha is mediated by TNF-R2." (PMID 30170620, 2018). "Blocking of the EGFR with cetuximab when tumor cells were stimulated with the type 1 cytokine IFNγ and TNFα resulted in the amplification of the production of the T-cell attracting chemokines and resulted in an increased migration of CD4+ and CD8+ lymphocytes in chemotaxis assays in vitro." (PMID 30192802, 2018). "However, treatment with Kanglaite alone caused almost no inhibition of epithelial mesenchymal transition -mediated tumor growth, when cells were pretreated with tumor necrosis factor-alpha prior to injection." (PMID 29467927, 2018). "Furthermore, TNF-α can directly affect tumor cells by increasing lysosomal enzymes and inducing apoptosis." (PMID 29361917, 2018). "TNF-α suppress tumor cell growth by inducing apoptosis in tumor cells." (PMID 30139984, 2018). "The median time to neoplasm from anti-TNF initiation was 5.0 years." (PMID 29540190, 2018). "The tumor necrosis factor (TNF)-related apoptosis-inducing ligand (TRAIL) is a member of the TNF superfamily deeply investigated for its ability to induce apoptosis in tumor cells but leaving normal cells virtually unaffected in favour of pro-survival pathways activation." (PMID 30204795, 2018).
tumor (continued). "Finally, both Mo-MDSCs and PMN-MDSCs differentiate into tumor-associated macrophages (TAMs), which facilitate tumor cell growth and survival via secreting IL-6, EGF, and TNF and promote angiogenesis by VEGFA, Semaphorin 4D, and IL-8." (PMID 29541408, 2018). "However, when the tumor cells were also stimulated with the type 1 cytokine IFNγ and TNFα an increased expression of CCL2, CCL5, CXCL9, CXCL10 and IL-6 was detected when compared to treatment with the control antibody." (PMID 30192802, 2018). "To this end, we found that the activation of NK cells by either tumor stimuli or cytokines in the presence of TGFβ induces potent NK cell anti-tumor IFNγ and TNFα secretion and alterations in NK cell cytotoxicity, corresponding to the downregulation of T-bet and SMAD3 expression." (PMID 30400618, 2018). "Upon exposure to inflammatory stimuli, TNF-alpha as well as IL-1 and other chemokines are produced mainly by activated macrophages and other cells of the myeloid lineage which attracts and activates neutrophils and monocytes to the tumor site." (PMID 30170620, 2018). "Of note, the transmembrane isoform of TNFα is also able to kill tumor cells." (PMID 30647851, 2018). "In addition there are some evidence from animal models that TNF in high concentration is capable of killing tumour cells." (PMID 29924765, 2018). "In addition to the induction of antitumor immune response, the cancer immunotherapy functions through the alteration of tumor microenvironment by the release of pro-inflammatory cytokines such as IL-12, IL-6, and TNF-α." (PMID 30081891, 2018). "As reported, TNF plays an important role in fighting against pathogens and tumor." (PMID 30713550, 2018). "The ability of infiltrated immune cells to promote tumor growth, progression, and immune surveillance may be mediated by several pro-inflammatory cytokines and chemokines, including TNFα, interleukin 17 (IL-17), IL-1, and CCL2 and CCL5." (PMID 30154786, 2018). "Specifically, targeting CAFs increases bioavailability of chemotherapeutic agents including doxorubicin and gemcitabine, while enabling immunological surveillance and tumor destruction through a process that engages interferon-gamma (IFNγ) and tumor necrosis factor alpha (TNF-α)." (PMID 28929459, 2018). "Interestingly, TNF-α is an inflammatory mediator, which has a tumor-promoting role in various stages of carcinogenesis, induces EMT mediated by TGF-β, promotes angiogenesis through the release of VEGF, and activates NF-kB signaling in models of cancer." (PMID 29703138, 2018). "Actually, TNF is even considered mostly as a pro-tumor cytokine." (PMID 29593717, 2018). "TAM could promote tumor angiogenesis and tumor growth through secretion of tumor necrosis factor alpha and VEGF." (PMID 30305076, 2018). "Additionally, PS is able to penetrate the blood brain barrier to act on TNFα, leading to the inactivation of NF-κB-targeted c-Met in brain-metastatic tumor tissues." (PMID 29346311, 2018). "Also, the level of inflammatory markers including TNFα, NF-κB p50 subunit and IL-4 in tumor tissues showed positive correlation with the level of ALCAM transcripts." (PMID 29315254, 2018). "The studies of chemokines, like CXCL 12 and TNF-α, as homing factors or adhesion inhibitors influencing the extravasation process, can be done by adding them either to the tumor cell suspension or into the reservoir, so as to collect the transmigrated tumor cells." (PMID 29882894, 2018). "It is reported that, Natural killer cells as well as T-cells expresses cytokines such as interferon-γ (IFN-γ), tumor necrosis factor-α (TNF-α) and interleukin-2 (IL-2) which in turn can induce PD-L1 expression on surrounding immune and tumor cells when T-cells recognize antigen and become activated." (PMID 29409471, 2018).